CFH (complement factor H)
Diseases named in the same sentence as CFH in open-access papers (continued):
Sharing a sentence is not in itself a finding about the gene and the disease.
age-related macular degeneration (continued). "It has been reported that CFH gene, an important regulator of the alternative complement cascade, is associated with age-related macular degeneration (AMD)." (PMID 17356516, 2007). "Nevertheless, genes with a different allelic architecture could be identified using such technology and, interestingly, a common disease haplotype has recently been associated with the common Y402H variant of Complement Factor H implicated in age-related macular degeneration." (PMID 17417609, 2007). "The genetics of more complex retinal diseases, such as glaucoma or age-related macular degeneration (AMD), were poorly understood until a breakthrough in 2005, when genetic variants in the complement factor H gene were identified as risk factors for AMD." (PMID 39943987, 2025). "One of the strongest links between CFH polymorphisms and disease is with age-related macular degeneration (AMD), where CFH polymorphisms are estimated to contribute to approximately 50% of AMD cases." (PMID 40309771, 2025). "Age-related macular degeneration (AMD) is a leading cause of vision loss; there is strong genetic susceptibility at the complement factor H (CFH) locus." (PMID 34260948, 2021). "Apart from CFH gene polymorphisms, ARMS2 gene SNP rs10490924 is associated with CSC, which suggests genetic overlap between age related macular degeneration (AMD) and CSC." (PMID 35052395, 2021). "P38 carried a heterozygous mutation in CFH (p.R53C), which had previously been found in patients with preeclampsia-related SHUa, in complement-related glomerulopathies and in familial forms of AMD (age-related macular degeneration, MIM 610698)." (PMID 32641076, 2020). "Genetic variants within complement factor H (CFH), a major alternative complement pathway regulator, are associated with the development of age-related macular degeneration (AMD) and other complementopathies." (PMID 32321835, 2020). "Polymorphisms in the Complement Factor H (CFH) gene, coding for the Factor H protein (FH), can increase the risk for age-related macular degeneration (AMD)." (PMID 32587311, 2020). "Blood samples from all subjects were genotyped for major age-related macular degeneration (AMD)-associated single nucleotide polymorphisms (SNPs) the major AMD-associated SNPs; CFH Y402H rs1061170, CFH I62V rs800292, ARMS2 A69S rs10490924." (PMID 30596689, 2018). "Recently, evidence has been accumulating regarding the association between genetic alterations in complement factor H (CFH) with the development of age-related macular degeneration (AMD) in clinical studies." (PMID 29497373, 2018). "While the aetiology of age-related macular degeneration (AMD)—a major blinding disease—remains unknown, the disease is strongly associated with variants in the complement factor H (CFH) gene." (PMID 30089174, 2018). "In light of this, it has recently been shown in a murine model of age related macular degeneration based on the complement factor h knock out mouse, that ATP production declines significantly prior to the development of the retinal phenotype." (PMID 26393878, 2015). "ARMS2, age-related maculopathy susceptibility 2 rs10490924; CFH, complement factor H rs1061170; SD, standard deviation." (PMID 25905023, 2015). "Variations in the CFH and CFHR1 genes have been studied for disease susceptibilities, including age-related macular degeneration, dense deposit disease, atypical hemolytic-uremic syndrome, and systemic lupus erythematosus (SLE)." (PMID 23894628, 2013). "CFH is one of several genes identified in genome-wide association studies to be implicated in age-related macular degeneration (AMD), the leading cause of irreversible blindness in the elderly." (PMID 23029250, 2012).
age-related macular degeneration (continued). "We chose the SNPs within 1 Mb from the complement factor H gene on chromosome 1q32, which was reported as a promising region for age-related macular degeneration." (PMID 22363789, 2012). "Complement factor H (CFH) is a central regulator of the complement system and has been implicated in the etiology of age-related macular degeneration (AMD), a leading cause of blindness in the elderly." (PMID 23029250, 2012). "Examples include identification of complement factor H (CFH) in age related macular degeneration, FGFR2 in breast cancer, and CDKN2A as well as CDKN2B in type 2 diabetes." (PMID 21247465, 2011). "The complement factor H (CFH) and the age-related macular susceptibility 2 (ARMS2) variants Y402H and A69S are major genetic risk and progression factors in age-related macular degeneration (AMD)." (PMID 21151600, 2010). "Variants in complement factor H (CFH), the hypothetical LOC387715, and the high-temperature requirement A-1 (HTRA1) genes have been reported to be associated with age-related macular degeneration (AMD)." (PMID 18682812, 2008). "Concerning rs35343172 CFH, in a study, multimodal imaging was used to identify phenotypic differences between carriers and noncarriers of rare CFH variants in age-related macular degeneration (AMD) patients." (PMID 40724958, 2025). "Moreover, complement factor D (CFD) and complement factor H (CFH) are important regulators of the complement system and are associated with diseases, such as age-related macular degeneration." (PMID 31861421, 2019). "Similarly, CFH/C3 DKO unexpectedly unmasks a more severe form of age-related macular degeneration in mice." (PMID 31604923, 2019). "Indeed, genes in the complement pathway, including complement factor H (CFH), C2/BF, and C3, are known to be associated with age-related macular degeneration (AMD)." (PMID 27748412, 2016). "Complement factor H (CFH) is one of the most important soluble complement regulatory proteins and is closely associated with age-related macular degeneration (AMD), the leading cause of irreversible central vision loss in the elderly population in developed countries." (PMID 26091360, 2015). "In the Stargardt patient with no pathogenic ABCA4 mutations two variants in CFH were detected, one of which (rs1061170) had previously been reported to predispose to age related macular degeneration (AMD)." (PMID 22277662, 2012). "One such example is an SNP in the complement factor H gene (rs1061170) which has a large effect size with age-related macular degeneration in Caucasians but much smaller in East Asian populations due to a remarkably lower risk allele frequency (∼35% in Caucasians and ∼5% in East Asians)." (PMID 19779542, 2009). "Recent findings that variants in complement factor H, B, complement component 2 (C2), and LOC387715/HTRA1 genes may increase the risk to develop age-related macular degeneration (AMD) provide insight into the pathological process of AMD." (PMID 17615538, 2007). "We have also characterized complement factor H (CFH) and CFI variants identified in patients with age-related macular degeneration (AMD), a leading cause of blindness in the developed world." (PMID 34912830, 2021). "CFH and HTRA1 genes are traditional markers of increased risk of age-related macular degeneration (AMD) across populations." (PMID 30257524, 2018). "In our patient we found two polymorphisms already known as pathogenic for C3GN in CFH (p.V62I in SCR1) and THBD (p.A473V) genes, as well as a polymorphism so far associated to age-related macular degeneration (AMD) in C3 (p.R102G)." (PMID 29592796, 2018). "The identification of vitronectin and CFH as tyrosine-sulfated proteins is significant, since both are deposited in drusen in the eyes of patients with age-related macular degeneration (AMD)." (PMID 25136834, 2014).
age-related macular degeneration (continued). "Remarkably, CFH-mediated inflammatory degeneration is characteristic of both Alzheimer's disease (AD) and age-related macular degeneration (AMD) and miRNA-146a and miRNA-155 are upregulated in both diseases." (PMID 24745005, 2014). "The complement factor H (CFH) gene has been recently confirmed to play an essential role in the development of age-related macular degeneration (AMD)." (PMID 17877809, 2007). "Genetic variants in the CFH and CFI genes that lead to haploinsufficiency (i.e., ~50% reductions in the levels of FH and FI) have been associated with age-related macular degeneration (AMD)." (PMID 32064578, 2020). "Next generation sequencing (NGS) showed polymorphism in CFH (p.V62I in SCR1) and THBD (p.A473V), already known as pathogenic for C3GN, as well as a mutation in C3 (p.R102G) associated only with age-related macular degeneration (AMD) so far." (PMID 29592796, 2018). "Reported seven years ago, the first demonstrated success of genome-wide association studies (GWAS) was the discovery of association between Y402 allele polymorphism in the complement factor H (CFH) gene and a 7.4-fold increased likelihood of developing age-related macular degeneration (AMD)." (PMID 24624293, 2013). "The genome-wide association studies showed that the common variants in CFH and CFH-related genes (CFHR1–5), and the haplotypes formed by these risk variants are significantly associated with the risk of age-related macular degeneration (AMD)." (PMID 22848687, 2012). "It has been postulated that variants in the CFH gene may be associated with CHD through modulation of inflammatory pathways, as has been reported in age-related macular degeneration (AMD) patients." (PMID 17877809, 2007). "Finally, the phenotype scanning uncovered connections between CFH (rs2274700) and age-related macular degeneration (AMD), lung function, B3GNT8 (rs284663) and height, coronary artery illness, basal metabolic rate, as well as CFHR4 (rs4915559) with neovascularization and AMD." (PMID 38778174, 2024). "The mechanism by which CFH SNPs influence the risk of IMD has not yet been fully determined; the common CFH Y402H polymorphism in CCP 7, which is involved in age-related macular degeneration, is adjacent to the fHbp binding site but does not affect CFH:fHbp interactions." (PMID 36941192, 2023). "The role of CRP has been implicated in the pathogenesis of age-related macular degeneration (AMD) by immunohistochemical evidence that showed clear changes in distribution and relative levels of CRP and complement factor H (CFH) in early and late AMD eyes." (PMID 23516433, 2013).
atypical hemolytic-uremic syndrome (39 papers, 2009 to 2026). "Mutations in the complement factor H (CFH) gene are associated with complement dysregulation and the development of atypical hemolytic uremic syndrome (aHUS)." (PMID 38524137, 2024). "Approximately 60% of cases of atypical hemolytic uremic syndrome are associated with deficiencies of the complement regulatory protein, including mutations in complement factor H, complement factor I, or the membrane co-factor protein." (PMID 35241161, 2022). "These diseases are: basal laminar drusen (AD), complement factor H deficiency (AR, AD), and atypical hemolytic uremic syndrome (AR, AD)." (PMID 33420067, 2021). "Deficiency, mutation or autoantibody of complement factor H have been linked to atypical hemolytic uremic syndrome that is characterized by thrombotic microangiopathy." (PMID 31134052, 2019). "Acquired deficiency or inactivating mutations of these soluble regulators, notably factor H (CFH), have been associated with a spectrum of glomerular disease, from Dense-deposit disease at one end to atypical hemolytic-uremic syndrome at the other." (PMID 22934182, 2012). "Mutations in SERPING1 cause hereditary angioedema, but there is no known phenotypic overlap with AMD such as had been established with atypical hemolytic uremic syndrome or glomerulonephritis arising in patients with mutations in CFH." (PMID 19169411, 2009). "Zhou and colleagues investigated the use of iPSC-ECs derived from patients with anti-complement factor H autoantibody-associated atypical hemolytic uremic syndrome (aHUS), an acquired autoimmune disease, with a high genetic predisposition, caused by dysregulation of the complement system." (PMID 41596430, 2026). "Autoantibodies against complement factor H (CFH), the key regulator of alternative complement pathway, have been described as being response for atypical hemolytic and uremic syndrome (aHUS), as well as being implicated in the development of C3 glomerulopathies (C3G)." (PMID 37322353, 2023). "However, recently published data have shown that CAPS is associated with variants in complement genes similar to those observed in atypical hemolytic-uremic syndrome—mostly, complement factor H mutations are described." (PMID 36675596, 2023). "Disease-causing variants in CFH result in 3 distinct pathologic syndromes: atypical hemolytic uremic syndrome, C3 glomerulopathy (a clinical entity that encompasses C3 glomerulonephritis and dense deposit disease, formerly membranoproliferative glomerulonephronophthitis type II), and AMD." (PMID 30905644, 2019). "Genetic analyses identify rare variants in complement regulators (CFH, CFI, MCP) and proteins (C5, C6), suggesting a shared mechanism between preeclampsia and complement-mediated disorders like atypical hemolytic uremic syndrome (aHUS)." (PMID 40777009, 2025). "We did however find polymorphism in the CFH gene, which has already been described in some patients with DDD, as well as CFH polymorphisms evidenced in patients with atypical hemolytic uremic syndrome." (PMID 27717365, 2016). "LOF variants in regulators of complement, such as CD46, CFH (factor H), and CFI (factor I), can result in hyperactivation of the complement pathway with increased consumption of C3, and patients frequently present with atypical hemolytic uremic syndrome (aHUS)." (PMID 40842819, 2025). "In patients with anti-complement factor H autoantibody-associated atypical hemolytic uremic syndrome (aHUS), these autoantibodies impair complement factor H normal regulatory function in the blood, leading to excessive complement activation on the endothelial surface." (PMID 41596430, 2026).
hemolytic-uremic syndrome (28 papers, 2006 to 2026). Acute kidney injury associated with microangiopathic hemolytic anemia and thrombocytopenia. "As an example, patients diagnosed with atypical Hemolytic Uremic Syndrome and with a positive genetic report identifying pathogenic variants in CFH, C3 or CFB genes, are at moderate to high risk of recurrence after transplantation." (PMID 36782285, 2023). "Mutations in the endothelial binding domain of CFH can manifest as an atypical hemolytic uremic syndrome (aHUS) resulting in alternative complement pathway-induced endothelial damage." (PMID 35682894, 2022). "Basal laminar drusen is the only ocular phenotype reported with a mutation in CFH, but variants can also produce complement factor H deficiency or hemolytic uremic syndrome." (PMID 35457050, 2022). "The second important observation was the resolution of hemolysis and improvement of the transplant function after receiving eculizumab in a 30-year-old woman with a CFH mutation who had a recurrence of the hemolytic-uremic syndrome in a kidney graft." (PMID 25319590, 2014). "Apart from the association with AMD, CFH mutations have been previously associated with renal diseases, the most common being membranoproliferative glomerulonephritis and hemolytic uremic syndrome, which can be also associated with an eye phenotype." (PMID 22277662, 2012). "Considering the potential diagnoses of TTP or hemolytic uremic syndrome (HUS), further tests were conducted, including the gene mutation analysis for coagulopathy and hematologic malignancies, measurement of sC5b-9, complement factor I and complement factor H levels, and ADAMTS13 activity." (PMID 39845832, 2024).
C3 glomerulopathy (24 papers, 2013 to 2024). "Alterations in each of the five CFHR genes combined with an intact CFH gene cause C3 glomerulopathy." (PMID 38772735, 2024). "Other complement abnormalities that have been identified as causes of C3 glomerulopathy include antibodies against factor B, CFH, and C3 convertase." (PMID 32824988, 2020). "Acquired causes of C3 glomerulopathy include antibodies affecting AP inhibition, such as anti-complement factor H or factor I, or those stabilising the activation of C3 convertase, such as C3 nephritic factor (C3Nef)." (PMID 25380644, 2014). "On the regulatory level, mutations in the CFH gene and anti-CFH autoantibodies have been identified in the C3 glomerulopathy patients and related to pathogenesis of the disease." (PMID 24030732, 2014). "We discuss the pathophysiology of C3 glomerulopathy, with evidence for alternative pathway dysregulation obtained from affected individuals and complement factor H (Cfh)-deficient animal models." (PMID 24161036, 2013). "In TMA, especially in aHUS, and C3 glomerulopathy, genetic sequencing studies have contributed to the identification of genetic variants involved in the complement pathways, such as: CFH, CFI, MCP/CD46, complement factor B (CFB), thrombomodulin (THBD), C3 and others." (PMID 39780910, 2024). "Dysregulation of the complement pathway—by genetic defects, mainly related to CFH or by autoimmune diseases, mainly related to autoantibodies (such as C3, C4, and C5 nephritic factors) against components of the pathway—results in C3 glomerulopathy." (PMID 39780910, 2024). "Accordingly, genetic and functional alterations of CFH were described in both atypical hemolytic uremic syndrome (aHUS) and C3 glomerulopathy (C3G)." (PMID 38398059, 2024). "Sequence and copy number variations in the CFHR gene cluster (CFH, CFHR1, CFHR2, CFHR3, CFHR4 and CFHR5) are linked to atypical hemolytic uremic syndrome (aHUS) and C3 glomerulopathy." (PMID 38772735, 2024). "It has previously been observed that C-terminal mutations in CFH are more associated with development of atypical hemolytic–uremic syndrome, and N-terminal mutations are more associated with AMD and C3 glomerulopathy." (PMID 37471073, 2023). "Autoantibodies targeting the plasma protein complement Factor H are reported in four glomerular diseases, C3 glomerulopathy, DEAP-HUS, TA-TMA, and membranous nephropathy." (PMID 34613485, 2021). "CFH mutations related to C3 glomerulopathy are particularly those leading to the absence of the functional component in plasma, and as a result to unrestricted alternative pathway activation." (PMID 24030732, 2014). "In patients with C3 glomerulopathy due to genetic mutations in CFH, chronic infusions of fresh frozen plasma to replace absent complement factors may be useful." (PMID 32824988, 2020).